DTHD1 (death domain containing 1)
Synonyms: FLJ16686
Tractability: No criterion of Open Targets' tractability assessment is met for any kind of drug.
Gene: Protein-coding gene on chromosome 4 (36,281,616 to 36,347,511, forward strand). Ensembl gene ENSG00000197057.
Gene Ontology:
Biological process: signal transduction
Genetic constraint (gnomAD): Loss-of-function variants: 63 observed, 75.16 expected, observed/expected ratio (o/e) 0.84, 90% interval 0.68 to 1.03. The upper end of that interval is the gene's LOEUF score, 1.03, which puts it in group 4 of 6, group 1 being the genes least tolerant of losing a copy. Missense variants: 1,024 observed, 1,050.6 expected, observed/expected ratio (o/e) 0.97, 90% interval 0.93 to 1.03. Synonymous variants: 357 observed, 364.94 expected, observed/expected ratio (o/e) 0.98, 90% interval 0.9 to 1.07.
Homologues: Orthologues: chimpanzee DTHD1 (98% identical), macaque DTHD1 (86% identical), pig DTHD1 (79% identical), dog DTHD1 (79% identical), rabbit DTHD1 (77% identical), mouse Dthd1 (75% identical), guinea pig DTHD1 (57% identical), tropical clawed frog dthd1 (41% identical), zebrafish dthd1 (27% identical). Paralogues in human: PSMD10 (6% identical).